IFT38 (intraflagellar transport 38)
Description:
Required for cilia biogenesis. Appears to function within the multiple intraflagellar transport complex B (IFT-B). Key regulator of hedgehog signaling.
Synonyms: CLUAP1; KIAA0643; FLJ13297; FAP22; CFAP22
Tractability: PROTAC: ubiquitination databases record sites on it.
Gene: Protein-coding gene on chromosome 16 (3,500,976 to 3,540,653, forward strand). Ensembl gene ENSG00000103351.
Subcellular location: Cell projection, cilium; Nucleus
Subcellular location (Human Protein Atlas): Nucleoplasm; Primary cilium; Actin filaments; Vesicles
Pathways (Reactome):
Organelle biogenesis and maintenance: Intraflagellar transport
Gene Ontology:
Molecular function: protein binding
Biological process: cilium assembly; intraciliary anterograde transport
Cellular component: cilium; intraciliary transport particle B; nucleoplasm; nucleus; ciliary tip; microtubule organizing center; centrosome; ciliary base; intraciliary transport particle A
Genetic constraint (gnomAD): Loss-of-function variants: 36 observed, 38.64 expected, observed/expected ratio (o/e) 0.93, 90% interval 0.71 to 1.23. The upper end of that interval is the gene's LOEUF score, 1.23, which puts it in group 5 of 6, group 1 being the genes least tolerant of losing a copy. Missense variants: 426 observed, 414.93 expected, observed/expected ratio (o/e) 1.03, 90% interval 0.95 to 1.11. Synonymous variants: 167 observed, 150.5 expected, observed/expected ratio (o/e) 1.11, 90% interval 0.98 to 1.26.
Homologues: Orthologues: chimpanzee CLUAP1 (99% identical), macaque CLUAP1 (98% identical), mouse Cluap1 (90% identical), guinea pig CLUAP1 (89% identical), rat Cluap1 (89% identical), pig CLUAP1 (87% identical), dog CLUAP1 (83% identical), rabbit CLUAP1 (81% identical), tropical clawed frog cluap1 (73% identical), zebrafish cluap1 (66% identical), Caenorhabditis elegans dyf-3 (38% identical), Drosophila melanogaster Cluap1 (34% identical).
Diseases named in the same sentence as IFT38 in open-access papers:
IFT38 is named in the same sentence as 22 diseases in open-access papers, as found by Europe PMC text mining. Sharing a sentence is not in itself a finding about the gene and the disease.
IFT38 shares sentences with these, for which no sentence is quoted: ciliopathies (3 papers); cancer (2); Obesity (2); retinal degeneration (2); asthma (1); Bardet-Biedl syndrome (1); cardiovascular diseases (1); Cerebellar atrophy (1); colon cancer (1); colorectal carcinoma (1); COVID-19 (1); developmental delay (1); diabetes (1); genetic disease (1); hypogonadism (1); infection (1); Joubert syndrome (1); Leber congenital amaurosis (1); leukemia (1); Oculomotor apraxia (1); thromboembolic disease (1); tumor (1).